USP9X (ubiquitin specific peptidase 9 X-linked)
Diseases named in the same sentence as USP9X in open-access papers (continued):
Sharing a sentence is not in itself a finding about the gene and the disease.
lung carcinoma (continued). "In our study, we found that USP9X is highly expressed and correlated with poor overall survival in lung cancer patients." (PMID 33558705, 2021). "For example, USP9X inhibits tumor formation in colon cancer, while it is highly expressed in lung cancer and various blood cancers." (PMID 33619866, 2021). "USP9X, also called FAM, is frequently dysregulated in multiple cancers and plays an oncogenic role in lung cancer progression." (PMID 33558705, 2021). "MiR-132 inhibits lung cancer cell migration and invasion by preventing USP9X-induced epithelial–mesenchymal transition." (PMID 33537240, 2020). "USP9X is excessive in tumor tissues such as follicular lymphoma, colon adenocarcinomas and lung cancers compared to the normal human tissues and has an impact on tumor progression." (PMID 24152793, 2013). "These phenotypes were partially reverted by exogenous overexpression of REV1, suggesting that USP9X could induce radioresistance in lung cancer cells by stabilizing REV1 expression." (PMID 38802791, 2024). "Moreover, both the data from the GEPIA database and the detection of protein expression in lung cancer tissue microarray confirmed that the expression of USP9X was positively correlated with REV1." (PMID 38802791, 2024). "Likewise, in GSE253742, MET, ETS-1, and USP9X expression levels in lung cancer tissues after osimertinib treatment were elevated compared to untreated lung cancer tissues, supporting our research findings." (PMID 39468027, 2024). "In addition, downregulation of USP9X also led to reduced levels of TGF-β2 mRNA in lung cancer cells." (PMID 33558705, 2021). "Importantly, restoration of KDM4C partially rescued the reduced levels of TGF-β2, p-Smad2 and p-Smad3 in USP9X-depleted lung cancer cells, suggesting that USP9X silencing inhibits TGF-β2/Smad signaling in a KDM4C-dependent manner." (PMID 33558705, 2021). "Moreover, we also uncovered that USP9X preferentially upregulates the protein levels of KDM4C by preventing its ubiquitination in lung cancer." (PMID 33558705, 2021). "In addition, our data also showed that USP9X-depleted lung cancer cells exhibited increased olive tail moment and enhanced radiosensitivity, and these phenotypes were also partially rescued by re-expressing KDM4C." (PMID 33558705, 2021). "In addition, we revealed that USP9X is involved in lung cancer progression and radioresistance in a KDM4C-dependent manner." (PMID 33558705, 2021). "Given that USP9X co-localized with KDM4C and a significant positive correlation between the expression of USP9X and KDM4C in lung cancer tissues was observed, we conclude that USP9X overexpression may account for KDM4C upregulation in human lung cancer." (PMID 33558705, 2021). "Importantly, we are the first to report that the deubiquitinase USP9X is responsible for the upregulation of KDM4C in lung cancer." (PMID 33558705, 2021). "To further clarify the role of USP9X-stabilized REV1 expression in lung cancer radioresistance and to elucidate whether this process is associated with alterations in the metabolic microenvironment, we transferred exogenously expressed REV1 into USP9X-deficient lung cancer cells." (PMID 38802791, 2024). "USP9X participates in TGF-β signaling by deubiquitylating Smad4 and TGFβR2, or by inducing TGF-β2 transcription, as shown in granulosa cells apoptosis and lung cancer radioresistance." (PMID 40246814, 2025). "Together, these results indicate that USP9X activates TGF-β2/Smad signaling and promotes radioresistance by stabilizing KDM4C in lung cancer cells." (PMID 33558705, 2021). "More importantly, depletion of USP9X impairs TGF-β2/Smad signaling and radioresistance by destabilizing KDM4C in lung cancer cells." (PMID 33558705, 2021). "Collectively, these results confirm that USP9X physically and specifically interacts with KDM4C in lung cancer cells." (PMID 33558705, 2021).
lung carcinoma (continued). "Accumulating evidence has revealed that USP9X is significantly up-regulated in human cancers, including pancreatic, breast, HCC, and lung cancers 54-57." (PMID 33767588, 2021). "Thus, our study satisfactorily explains the aberrant expression of REV1 in lung cancer cells, i.e., overexpression of REV1, a newly identified USP9X substrate, is the result of USP9X-mediated deubiquitination." (PMID 38802791, 2024). "Mechanistically, the ubiquitination compound library screening system identified the USP9X deubiquitinase as a novel upstream REV1 regulatory protein, and that USP9X mediated REV1 deubiquitination modifications to stabilize its expression in lung cancer." (PMID 38802791, 2024). "Furthermore, knockdown of USP9X in two different lung cancer cell lines resulted in the downregulation of REV1 expression, suggesting positive regulation of REV1 by USP9X." (PMID 38802791, 2024). "In addition, we also showed the presence of an endogenous interaction between USP9X and KDM4C in lung cancer cells." (PMID 33558705, 2021). "Importantly, the knockdown of USP9x did not induce cell death in either of the tested lung cancer cell lines." (PMID 39075050, 2024). "Furthermore, the impact of USP9x silencing on cell growth was measured in additional NSCLC cell lines, namely A549 and NCI-H2087, revealing a similar growth reduction as in NCI-H1975 lung cancer cells." (PMID 39075050, 2024). "To further clarify the role of USP9X in lung cancer radioresistance and confirm whether this effect is dependent on KDM4C, we transfected exogenously expressed KDM4C into USP9X-depleted cells and found that TGF-β2, p-Smad2 and p-Smad3 protein levels were decreased when USP9X was knocked down." (PMID 33558705, 2021). "Thus, our findings demonstrate that USP9X-mediated KDM4C deubiquitination activates TGF-β2/Smad signaling to promote radioresistance, suggesting that targeting KDM4C may be a promising radiosensitization strategy in the treatment of lung cancer." (PMID 33558705, 2021). "Consistently, western blot analysis of 22 lung cancer and 33 ovarian cancer cell lines revealed that both USP13 and MCL1, but not USP9X, were ubiquitously expressed at the protein level." (PMID 29335437, 2018).
glioblastoma (17 papers, 2014 to 2025). The most malignant astrocytic tumor (WHO grade IV). "Indeed, in certain glioblastoma cell lines, it has been demonstrated that USP9X loss regulates radiosensitivity by Mcl-1-independent mechanisms." (PMID 34277417, 2021). "In glioblastoma, USP9X maintains mesenchymal identity of CSCs and promotes ionizing radiation or temozolomide resistance through deubiquitylating ALDH1A3." (PMID 40246814, 2025). "Significantly, USP9X is involved in maintaining the stemness maintenance of glioblastoma stem cells." (PMID 37053008, 2023). "Our results show a different requirement of USP9x in the control of glioblastoma cell survival and radiosensitivity." (PMID 26775694, 2016). "Our findings showed that interference with Usp9X signaling rendered glioblastoma cell cultures sensitive to TRAIL-mediated apoptosis, which to the best of our knowledge has not been reported thus far for any tumor entity." (PMID 26872380, 2016). "A more detailed mosaic plot analysis of Mcl-1 and USP9x IRS shows that Mcl-1 was upregulated in more glioblastoma tissue samples and to a greater extent than USP9x." (PMID 26775694, 2016). "Mechanistically, the genetic and pharmacological interference with Usp9X leads to a strong activation of apoptosis with initiator- and effector caspase activation in different types of glioblastoma model systems." (PMID 26872380, 2016). "Pharmacological and genetic interference with Usp9X efficiently sensitized glioblastoma cells to intrinsic and extrinsic apoptotic stimuli." (PMID 26872380, 2016). "All four glioblastoma cell lines expressed USP9x as well as antiapoptotic Mcl-1, Bcl-2, Bcl-xL, and pro-apoptotic Bax, Bak, Noxa, Puma, and Bad." (PMID 26775694, 2016). "These molecular alterations following a treatment with WP1130 were mirrored when silencing Usp9X with siRNA in SF188 pediatric glioblastoma cells." (PMID 26872380, 2016). "Taken together, our findings highlight that targeting Usp9X for glioblastoma is feasible and that inhibition of Usp9X alone or along with other compounds significantly impairs the growth of preclinical models of glioblastoma in vitro and in vivo." (PMID 26872380, 2016). "Yet, Mcl-1 and USP9x IRS correlated moderately but significantly in grade IV glioblastoma (Spearman correlation, ρ=0.47, P=0.0063), indicating a coincidental upregulation of Mcl-1 and USP9x." (PMID 26775694, 2016). "Immunohistochemical analysis shows that number of Mcl-1- and USP9x-positive cells and staining intensity were significantly upregulated in glioblastoma compared with astrocytoma." (PMID 26775694, 2016). "Correlating Mcl-1 and USP9x expressions were significantly higher in human glioblastoma than in astrocytoma." (PMID 26775694, 2016). "Combined treatment with L-asparaginase and TRAIL yielded a marked down-regulation of Mcl-1 and Usp9X in LN229 glioblastoma cells." (PMID 27172899, 2016). "Our present study extends these findings and provides significant additional insight on the role of Usp9X in glioblastoma biology." (PMID 26872380, 2016). "Overall, these observations reinforce the notion that interference with the Usp9X signaling axis confers a pro-apoptotic state in various glioblastoma cell culture models." (PMID 26872380, 2016). "In the present study, we aimed to analyze the impact of USP9x on Mcl-1 and cell survival in glioblastoma cell lines." (PMID 26775694, 2016). "In silico analysis revealed that DNA copy number or mRNA expression of Usp9X is significantly increased in glioblastoma and anaplastic astrocytoma when compared to normal brain." (PMID 26872380, 2016). "The protein levels of USP9x and Mcl-1 were slightly but insignificantly higher in five of six glioblastoma cell lines than in Jurkat cells." (PMID 26775694, 2016). "Expression analysis data confirm that Usp9X expression is increased in glioblastoma compared to normal brain tissue indicating its potential as a therapeutic." (PMID 26872380, 2016).
glioblastoma (continued). "Specific down-regulation of Usp9X reduces viability in glioblastoma cells mimicking the effects of WP1130." (PMID 26872380, 2016). "We conclude that USP9x can control survival and radiosensitivity in glioblastoma cells by Mcl-1-dependent and Mcl-1-independent mechanisms." (PMID 26775694, 2016). "Our data show that GX15-070 was remarkably efficacious in suppressing Usp9X protein levels in glioblastoma cells." (PMID 26008975, 2015). "It is notable that our study is the first to demonstrate that single knock-down of both Bag3 and Usp9X are sufficient to sensitize glioblastoma cells to BH3-mimetics." (PMID 26008975, 2015). "Given that we and others demonstrated an apoptosis-inducing effect on glioblastoma cells subsequent to Usp9X-silencing, we believe that it is worthwhile considering Usp9X as a future therapeutic target." (PMID 26008975, 2015). "Our results show that knock-down of both Bag3 and Usp9X leads to a depletion of Mcl-1 protein levels in glioblastoma cells and rendered them highly sensitive to ABT263." (PMID 26008975, 2015). "Our data confirms the previous notion that knocking down Usp9X suppresses Mcl-1 along with Bcl-2 and primes glioblastoma cells to ABT263." (PMID 26474387, 2015). "Next we silenced Usp9X in LN229 glioblastoma cells to determine the impact of Usp9X on the chaperone Bag3 as well as initiator- and effector caspases." (PMID 26008975, 2015). "Glioblastoma (GBM) growth relies on glutamine synthetase (GS), which is stabilized by histone deacetylase 6 (HDAC6) and deubiquitinated by ubiquitin‐specific peptidase 9, X‐linked (USP9X)." (PMID 40162736, 2025). "We previously identified USP9x as a factor regulating radiosensitivity in glioblastoma cells." (PMID 37173959, 2023). "To assess whether the WP1130-mediated down-regulation of Mcl-1 and Usp9X is due to a transcriptional mechanism we performed real-time PCR analyses in U251 glioblastoma cells following treatment with WP1130." (PMID 26872380, 2016). "Thus, our data indicate that USP9x has a role during tumor progression from astrocytoma to glioblastoma." (PMID 26775694, 2016). "Consequently, we show in this study that interference with deubiquitinases, such as Usp9X, results in a marked anti-proliferative and pro-apoptotic effect on established, glioma stem-like and primary patient-derived xenograft glioblastoma cells." (PMID 26872380, 2016). "Although Mcl-1 knockdown by siRNA increased apoptosis induction after irradiation in all glioblastoma cell lines, USP9x knockdown significantly improved radiation-induced apoptosis in one of four cell lines and slightly increased apoptosis in another cell line." (PMID 26775694, 2016). "Comparing human grade III astrocytoma with grade IV glioblastoma samples, we could show that Mcl-1 and USP9x are upregulated during tumor progression." (PMID 26775694, 2016). "Here we analyzed the impact of USP9x on Mcl-1 levels and radiosensitivity in glioblastoma cells." (PMID 26775694, 2016). "However, siRNA mediated knock-down of Usp9X in glioblastoma cells recapitulates the effects of WP1130, suggesting that WP1130 significantly mediates its anti-glioma effects by interference with Usp9X function." (PMID 26872380, 2016). "However, in the context of established pancreatic cancer cell line model systems Usp9X appears to have pro-survival functions, which is also in line with our findings in various glioblastoma models." (PMID 26872380, 2016). "Here, we target deubiquitinases for glioblastoma therapy by utilizing the small-molecule inhibitor WP1130 which has been characterized as a deubiquitinase inhibitor that interferes with the function of Usp9X." (PMID 26872380, 2016).
glioblastoma (continued). "In glioblastoma, only little is known about the role of Usp9X and other deubiquitinases." (PMID 26872380, 2016). "Our data show that USP9x regulates radiosensitivity only in some glioblastoma cells." (PMID 26775694, 2016). "USP9x expression correlated moderately but significantly with Mcl-1 expression in glioblastoma, supporting our hypothesis that USP9x stabilizes Mcl-1 in glioblastoma cells." (PMID 26775694, 2016). "After measuring the influence of USP9x on irradiated glioblastoma cells in a short-term assay, we analyzed the influence of USP9x on long-term survival by a colony-formation assay measuring the clonogenic survival upon transfection with USP9x siRNA or the non-targeting control siRNA and irradiation." (PMID 26775694, 2016). "In order to further examine whether the anti-proliferative effect on glioblastoma cells following a treatment with WP1130 can be recapitulated by specific knock-down of Usp9X we performed siRNA experiments." (PMID 26872380, 2016). "There is minimal information on Usp9X signaling in glioblastoma cells." (PMID 26008975, 2015). "The deubiquitinating enzyme Usp9X was shown to be overexpressed in various human cancers, including glioblastoma, which supports the notion that deubiquitinating enzymes represent a valid target in this disease and that their inhibition may add to a concerted strategy against glioblastoma." (PMID 26872380, 2016). "Thus, targeting both Bag3 and Usp9X may represent novel approaches to overcome intrinsic and potentially extrinsic apoptotic resistance in glioblastoma." (PMID 26008975, 2015). "In another highly aggressive tumor, glioblastoma (GBM), USP9X interacts with aldehyde dehydrogenase one family member A3 (ALDH1A3) and stabilizes it to promote the tumorigenic capacity of mesenchymal stem cells." (PMID 34405018, 2021). "We show that the Usp9X inhibitor, WP1130, exerts anti-glioma activity in established, stem cell-like glioma, proneural and patient-derived glioblastoma xenograft cells." (PMID 26872380, 2016). "As anticipated, treatment with WP1130 lead to down-regulation of Usp9X in a dose-dependent manner in SF188, U251 and T98G glioblastoma cells." (PMID 26872380, 2016). "USP8 and USP9X deubiquitinate ITCH to induce ubiquitination and degradation of the anti-apoptotic protein c-FLIP, leading to apoptosis in glioblastoma, or to anoikis in pancreatic ductal adenocarcinoma." (PMID 27203743, 2016). "In the first set of experiments, we examined the expression of Mcl-1 and USP9x in astrocytoma (WHO grade III) and glioblastoma (WHO grade IV)." (PMID 26775694, 2016). "Therefore, we performed siRNA experiments down-regulating protein expression of Usp9X in GBM12 patient-derived glioblastoma cells and SF188 pediatric glioblastoma cells." (PMID 26872380, 2016). "However, not all glioblastoma tissue samples expressing high Mcl-1 levels also express high USP9x levels." (PMID 26775694, 2016). "Similarly, USP9X expression is required to maintain growth of glioblastomas and medulloblastomas, but USP9X-dependent growth does not appear to involve Mcl-1 stabilization." (PMID 25606592, 2014).